ACKR2 (atypical chemokine receptor 2)
Description:
Atypical chemokine receptor that controls chemokine levels and localization via high-affinity chemokine binding that is uncoupled from classic ligand-driven signal transduction cascades, resulting instead in chemokine sequestration, degradation, or transcytosis. Also known as interceptor (internalizing receptor) or chemokine-scavenging receptor or chemokine decoy receptor. Acts as a receptor for chemokines including CCL2, CCL3, CCL3L1, CCL4, CCL5, CCL7, CCL8, CCL11, CCL13, CCL17, CCL22, CCL23, CCL24, SCYA2/MCP-1, SCY3/MIP-1-alpha, SCYA5/RANTES and SCYA7/MCP-3. Upon active ligand stimulation, activates a beta-arrestin 1 (ARRB1)- dependent, G protein-independent signaling pathway that results in the phosphorylation of the actin-binding protein cofilin (CFL1) through a RAC1-PAK1-LIMK1 signaling pathway. Activation of this pathway results in up-regulation of ACKR2 from endosomal compartment to cell membrane, increasing its efficiency in chemokine uptake and degradation. By scavenging chemokines in tissues, on the surfaces of lymphatic vessels, and in placenta, plays an essential role in the resolution (termination) of the inflammatory response and in the regulation of adaptive immune responses. Plays a major role in the immune silencing of macrophages during the resolution of inflammation (By similarity). Acts as a regulator of inflammatory leukocyte interactions with lymphatic endothelial cells (LECs) and is required for immature/mature dendritic cells discrimination by LECs.
Synonyms: CCBP2; CCR10; CMKBR9; D6; CCR9; hD6
Tractability: Small molecule: it belongs to a druggable protein family. Antibody: its Gene Ontology location is reachable by antibodies, with high confidence; UniProt places it where antibodies can reach, with medium confidence; UniProt predicts a signal peptide or a membrane-spanning region.
Target class: Chemokine receptor; Peptide receptor (family A GPCR); Family A G protein-coupled receptor; CC chemokine receptor; Membrane receptor
Gene: Protein-coding gene on chromosome 3 (42,804,586 to 42,887,974, forward strand). Ensembl gene ENSG00000144648.
Subcellular location: Early endosome; Recycling endosome; Cell membrane
Subcellular location (Human Protein Atlas): Cytosol; Vesicles; Nucleoplasm
Pathways (Reactome):
Signal Transduction: Chemokine receptors bind chemokines
Gene Ontology:
Molecular function: chemokine receptor activity; protein binding; receptor decoy activity; C-C chemokine binding; C-C chemokine receptor activity; G protein-coupled receptor activity
Biological process: calcium-mediated signaling; cell chemotaxis; immune response; intracellular signal transduction; positive regulation of cytosolic calcium ion concentration; chemokine-mediated signaling pathway; chemotaxis; G protein-coupled receptor signaling pathway
Cellular component: actin filament; cytosol; early endosome; plasma membrane; recycling endosome; external side of plasma membrane; membrane
Genetic constraint (gnomAD): Loss-of-function variants: 1 observed, 0.38 expected, observed/expected ratio (o/e) 2.63. That is too few expected variants to judge how well the gene tolerates losing a copy. Missense variants: 455 observed, 504.47 expected, observed/expected ratio (o/e) 0.9, 90% interval 0.83 to 0.98. Synonymous variants: 207 observed, 204.05 expected, observed/expected ratio (o/e) 1.01, 90% interval 0.9 to 1.14.
Homologues: Orthologues: chimpanzee ACKR2 (98% identical), macaque ACKR2 (95% identical), rabbit ACKR2 (82% identical), pig ACKR2 (79% identical), guinea pig ACKR2 (77% identical), rat Ackr2 (72% identical), mouse Ackr2 (72% identical), zebrafish ACKR2 (27% identical). Paralogues in human: CCR4 (35% identical), CCR1 (34% identical), CCR3 (32% identical), CX3CR1 (32% identical), CCR2 (31% identical), CCR5 (31% identical), CCR8 (31% identical), CCR6 (30% identical), XCR1 (30% identical), CXCR2 (30% identical), CXCR3 (30% identical), CCR10 (29% identical), and 11 more.
Diseases named in the same sentence as ACKR2 in open-access papers:
ACKR2 is named in the same sentence as 86 diseases in open-access papers, as found by Europe PMC text mining. Sharing a sentence is not in itself a finding about the gene and the disease. The quoted sentences say what the papers report.
breast carcinoma (18 papers, 2013 to 2025). "In breast cancer and in many other malignancies, ACKR2 expression was causatively linked to down-regulation of tumor growth and metastasis." (PMID 32582148, 2020). "In line with previous carcinogenesis results, in an oncogene-driven mammary carcinoma model we found that ACKR2-deficient mice show enhanced tumor growth at the primary tumor site." (PMID 29445158, 2018). "In agreement with this set of previous data we found that in a model of primary mammary carcinogenesis driven by Her2, an oncogene involved in human breast cancer, ACKR2 deficiency was associated with accelerated appearance and growth of primary lesions." (PMID 29445158, 2018). "ACKR2 deficiency results in neutrophil-mediated protection against metastasis in mice orthotopically transplanted with 4T1 mammary carcinoma and intravenously injected with B16F10 melanoma cell lines." (PMID 29445158, 2018). "Regarding the impact of SNPs in the ACKR2 gene on cancer, it has been shown that rs2228468 is correlated with breast cancer metastasis." (PMID 35677043, 2022). "The anti-tumor effects of ACKR2 on breast cancer have been attributed to its anti-inflammatory function." (PMID 35677043, 2022). "In mice orthotopically implanted with 4T1 mammary cancer and intravenously injected with B16F10 melanoma cell lines, ACKR2 loss resulted in neutrophil-mediated protection against metastasis." (PMID 35677043, 2022). "ACKR2 retains and regulates myeloid cell differentiation and function, and the direct targeting of host ACKR2 enhances the ability of neutrophils to specifically attack lung metastases, as shown in a breast cancer mouse model." (PMID 34885082, 2021). "Overexpression of ACKR2 inhibited proliferation and invasion of breast cancer cells in vitro as well as reduced lung metastasis in vivo." (PMID 32456359, 2020). "Here the authors confirm that ACKR2 depletion promotes primary tumor growth but show it has an anti-metastatic effect in mouse models of breast cancer by affecting myeloid differentiation and unleashing the anti-metastatic activity of neutrophils." (PMID 29445158, 2018). "Tubule cell staining for ACKR2 is unsurprising considering ACKR2 has been shown in parenchymal cells of several organs: ACKR2 antibodies stain epidermis in psoriatic skin, syncytiotrophoblast cells of placenta, and breast cancer cells." (PMID 26798651, 2016). "ACKR2 was also found to be expressed in human breast cancer, and its expression predicts relapse-free survival (RFS) while it is inversely correlated with axillary lymph node metastasis." (PMID 28123388, 2016). "It was also demonstrated that ACKR2 may play a protective role in breast cancer, reducing its proliferation and metastatic potential." (PMID 32456359, 2020). "Recent studies have suggested that the G protein-coupled receptor GPR85 and atypical chemokine receptor 2 (ACKR2) could be the target of CXCL14 in breast cancer cells." (PMID 32708730, 2020). "Of note, a functional non-synonymous single nucleotide polymorphism of ACKR2 is associated with lymph node metastasis and RFS in breast cancer, indicating that the expression and function of ACKR2 in the host could also affect tumor progression." (PMID 28123388, 2016). "In this cancer, expression of ACKR2 was accompanied by ACKR1 and ACKR4 which were negatively correlated to axillary lymph node metastasis of breast tumor cells, suggesting favorable outcomes for co-expression of ACKR2, DARC, and CCX-CKR in breast cancer." (PMID 35677043, 2022). "This is illustrated by a recent study demonstrating that fibroblast-derived CXCL14 acted in the context of tumor cell expressed ACKR2, activating the ERK pathway and inducing EMT, elevating migration and lung colonization by luminal-A breast cancer cells." (PMID 32582148, 2020).
breast carcinoma (continued). "During the preparation of our manuscript, a paper was published, which describes the role of fibroblast-derived CXCL14 in EMT and metastasis of breast cancer, and identifies the GPCR ACKR2 as a mediator for CXCL14 action." (PMID 31117166, 2019). "Additionally, ACKR2 has been identified as a receptor for exogenous CXCL14 in lung and breast cancers, where it contributes to the activation of tumor cell invasion and migration." (PMID 40898244, 2025). "Furthermore, ACKR2 is a receptor responsible for CXCL14-induced EMT and metastasis in breast cancer." (PMID 37056937, 2023). "Both ACKR2 and CCR1 have been shown to be important in the progression of breast cancer; therefore, understanding early interactions between these receptors could reveal key insights, which drive later pathology." (PMID 32467242, 2020). "Although there is no defined correlation of ACKR2 expression with other carcinogenic factors in cervical cancer, ACKR2 downregulation has been accompanied by dysregulation of metastatic factors such as MMP9 and VEGF in breast cancer." (PMID 35677043, 2022).
psoriasis (11 papers, 2013 to 2023). An autoimmune condition characterized by red, well-delineated plaques with silvery scales that are usually on the extensor surfaces and scalp. "Altered ACKR2 function has been implicated in several inflammatory disorders, including psoriasis, a common and debilitating T-cell–driven disorder characterized by thick erythematous skin plaques." (PMID 29279330, 2018). "Here, we identified specific psoriasis-associated microRNAs (miRs) that bind ACKR2, inhibit its expression, and are active in primary cultures of human cutaneous cells." (PMID 29279330, 2018). "ACKR2 (Atypical chemokine receptor 2), previously known as the chemokine-scavenging receptor D6, is a scavenger receptor for CC chemokines that has been associated with various inflammatory diseases, including psoriasis." (PMID 30744173, 2019). "ACKR2 was upregulated in lesional PsA skin but in contrast to previous psoriasis studies, its expression was unchanged in uninvolved skin compared with HC skin." (PMID 37131254, 2023). "The distribution of ACKR2-expressing cells PsA skin was also different to previous observations in psoriasis; the current study identified sparse expression in HC skin with a similar pattern in PsA-uninvolved skin." (PMID 37131254, 2023). "In psoriasis lesions, there was also expression of ACKR2 throughout the epidermis, but in our PsA lesional samples, most ACKR2-expressing cells were found in the suprabasal epidermis." (PMID 37131254, 2023). "The scavenging receptor ACKR2 has previously been identified as a potential regulator of cutaneous inflammation in psoriasis with a two-fold increased expression in psoriasis skin lesions and > tenfold upregulation in psoriasis uninvolved skin." (PMID 37131254, 2023). "ACKR2 expression is further downregulated in psoriasis patients after cell damage, which is a key trigger for the creation of new plaques (also called the Koebner phenomenon)." (PMID 35677043, 2022). "ACKR2 expression is elevated in many human inflammatory conditions, including rheumatoid arthritis, systemic sclerosis, and psoriasis." (PMID 29279330, 2018). "We propose a mechanism by which cell trauma and miRs coordinately exacerbate inflammation via down-regulation of ACKR2 expression and provide a putative mechanistic explanation for the Koebner phenomenon in psoriasis." (PMID 29279330, 2018). "This was also the case for IFNγ-pretreated KCs, suggesting that KCs with elevated ACKR2 levels such as those found in psoriasis patients display tensile stress–induced down-regulation of expression." (PMID 29279330, 2018). "Here, we identify microRNAs that are both differentially expressed in psoriasis and predicted to target the ACKR2 3′-UTR." (PMID 29279330, 2018). "Psoriasis patients have markedly elevated T-cell cytokines, including IFNγ, that correlate with elevated ACKR2 in unaffected skin." (PMID 29279330, 2018). "This, coupled with previous observations from psoriasis and SSc patients suggests that elevated ACKR2 levels are a consistent feature of many human inflammatory pathologies." (PMID 28486662, 2017). "In keeping with our data from human psoriasis, ACKR2 expression was reduced within psoriasis-like inflammatory lesions of IMQ-treated skin compared with noninflamed skin." (PMID 27568525, 2017). "We have also previously shown marked up-regulation of ACKR2 expression in the epidermis and peripheral blood in psoriasis, and whole skin and peripheral blood in systemic sclerosis." (PMID 28486662, 2017). "Accordingly, we propose that developing specific inducers of ACKR2 chemokine scavenging provides a new therapeutic approach to treat diseases such as psoriasis and possibly other systemic inflammatory disorders." (PMID 27568525, 2017). "We then examined how adding variable numbers of activated T-cells affected ACKR2 transcript expression in an in vitro human skin equivalent model of psoriasis." (PMID 27568525, 2017).
psoriasis (continued). "Together, these data show that ACKR2 is required for limiting inflammation in a relevant in vivo model of psoriasis." (PMID 27568525, 2017). "ACKR2 has been proposed as a regulator of cutaneous inflammation in psoriasis." (PMID 37131254, 2023). "The inflammatory CC chemokine scavenging receptor ACKR2 has been proposed as a regulator of cutaneous inflammation in psoriasis with a two-fold increased expression in psoriasis skin lesions and > tenfold upregulation in psoriasis uninvolved skin, with reduced expression following mild trauma." (PMID 37131254, 2023). "The findings do however suggest a potential differential role of ACKR2 in psoriasis and PsA skin, and it could be postulated that a dysregulation of ACKR2 in PsA skin may allow the spread of inflammation beyond the skin." (PMID 37131254, 2023). "Chemokines and the CC chemokine scavenger receptor ACKR2 are upregulated in uninvolved psoriasis." (PMID 37131254, 2023). "Previous work demonstrated that the expression of ACKR2 in uninvolved skin in psoriasis could be reduced by mild trauma, representing a potential mechanism for the Koebner phenomenon observed in this condition." (PMID 37131254, 2023). "The increased ACKR2 expression in PsA skin lesions with unchanged expression in PsA uninvolved skin compared to HC skin was unexpected, as this contrasts with previous work in psoriasis skin, which showed strong upregulation in uninvolved skin in psoriasis." (PMID 37131254, 2023). "Furthermore, the authors showed that cell trauma, a well-known trigger for psoriasis, also leads to decreased expression of ACKR2." (PMID 30744173, 2019). "Moreover, as a result of miR-146b and miR-10b, keratinocytes in psoriasis produce less level of the atypical chemokine receptor 2 (ACKR2), a scavenger of pro-inflammatory chemokines." (PMID 30322050, 2018). "Moreover, we demonstrate that ACKR2 expression is further down-regulated upon cell trauma, an important trigger for the development of new plaques in many psoriasis patients (the Koebner phenomenon)." (PMID 29279330, 2018). "Taken together, these data suggest that KCs exposed to psoriasis-associated T-cell cytokines markedly up-regulate miR-146a/b expression concurrently with ACKR2 down-regulation upon stretching and provide a putative mechanistic link that explains the Koebner phenomenon in psoriasis." (PMID 29279330, 2018). "In psoriasis, ACKR2 is highly up-regulated in clinically unaffected remote skin." (PMID 27568525, 2017). "Together our data suggest that remotely increasing ACKR2 expression levels limits development of cutaneous inflammatory responses and, therefore, highlight a potential therapeutic role in psoriasis and other inflammatory diseases for agents capable of inducing ACKR2 expression." (PMID 27568525, 2017). "The dynamics of psoriasis-like pathology during induction of inflammation was quantified using a modified Psoriasis Area Severity Index (PASI), which showed that ACKR2-deficient mice rapidly develop substantially worse pathology than WT mice." (PMID 27568525, 2017). "We next wanted to determine whether ACKR2 expression is differentially modulated in the in vivo IMQ model of psoriasis." (PMID 27568525, 2017). "This evidence enables the speculation that ACKR2 could be considered as a potential therapeutic target to be induced in order to attenuate inflammation, e.g., during psoriasis and lung infection." (PMID 28123388, 2016). "ACKR2 induction might therefore be a promising therapeutic strategy in psoriasis." (PMID 30744173, 2019). "ACKR2 is an important regulator of inflammation and we have previously reported marked upregulation of expression in skin and peripheral blood leucocytes in psoriasis and SSc, and others have shown increased expression in chronic obstructive pulmonary disease and post-myocardial infarction tissues." (PMID 28486662, 2017). "Similarly increased levels of ACKR2 have been reported in psoriasis and SSc." (PMID 28486662, 2017).
psoriasis (continued). "miR-146a and -b are differentially expressed in psoriasis, suggesting non-redundant roles in this context, although our in silico analyses predicted that miR-146a and miR-146b both bind the ACKR2 3′-UTR." (PMID 29279330, 2018). "To establish a mouse model appropriate for assessing the mechanism of differential ACKR2 regulation and the role of ACKR2 in regulating localized inflammation, we determined the role of ACKR2 in the well-characterized imiquimod (IMQ) mouse model of psoriasis." (PMID 27568525, 2017). "Using a psoriasis-like skin inflammation model induced by imiquimod, it has been shown that localized inflammation and IFN-γ induce the upregulation of ACKR2 in remote tissues that control the spread of psoriasiform inflammation inhibiting T cell epidermal influx." (PMID 28123388, 2016). "In contrast to previous psoriasis studies, ACKR2 was not upregulated in uninvolved PsA skin." (PMID 37131254, 2023).